APOE (apolipoprotein E)
Diseases named in the same sentence as APOE in open-access papers (continued):
Sharing a sentence is not in itself a finding about the gene and the disease.
dementia (continued). "To verify whether the APOE gene played a role as an effect modifier in the PPI use and dementia associations, we conducted subgroup analysis in different APOE ε4 genotypes by the fully adjusted model and tested the interactions." (PMID 36045363, 2022). "The relationship among ApoE, dementia, and comorbidities seems to be complex." (PMID 36578446, 2022). "Nevertheless, the role of the APOE ε4 allele in SVD and dementia is still not well understood." (PMID 35912087, 2022). "In PD, the APOE ε4 allele has been also associated with earlier disease onset and a greater risk of dementia, although there is also evidence that does not confirm these relationships." (PMID 35741861, 2022). "Of all dementia cases, 69 (25.5%) had the diagnosis of AD and 109 (40.2%) were APOE-ε4 carriers." (PMID 35093034, 2022). "Interestingly, IPA showed activation of dementia and AD‐related pathways in AD APOE ε4 carrier lymphocytes." (PMID 33939248, 2021). "Participants with missing or unknown values for APOE genotype, prevalent dementia, missing or unknown values for level of intellectual disability, and missing or unknown values for dementia diagnosis and AD diagnosis were excluded." (PMID 34279450, 2021). "These associations were independent of age, sex, education, and APOE status, factors that over the years have been indicated as being strong predictors of cognitive impairment and dementia." (PMID 34404456, 2021). "One recent study found that healthy lifestyle profiles were associated with lower risks of dementia only among apolipoprotein E (APOE) ε4 noncarriers, but not among carriers." (PMID 34061824, 2021). "The hazards ratio of dementia risk for current and former versus never smokers remained nearly unchanged after the additional adjustment of APOE genotype and polygenic risk (HR 1.37; 95% CI 1.14–1.65 and HR 1.19; 95% CI 1.06–1.32, respectively)." (PMID 34155245, 2021). "Both healthy lifestyle profile and lower genetic dementia risk, represented by not carrying the APOE ε4 allele, were associated with lower odds of cognitive impairment." (PMID 34061824, 2021). "Although the association between frailty and dementia appears robust and seemingly independent of other risk factors, the role of familial environmental factors and genetic predisposition, other than APOE, in the association has not been studied." (PMID 34657626, 2021). "In the oldest-old, APOE ε2 has been associated with decreased risk of clinical dementia and absence of β-amyloid on PET imaging, but not a significant decrease in the neuropathologic burden." (PMID 33786000, 2021). "The relationship between higher concentrations of EPA and a decreased risk for incident all-cause dementia was significant among APOE ε4 noncarriers (Model 2: HR = 0.76, 95% CI 0.61, 0.94) but not among APOE ε4 carriers." (PMID 33573174, 2021). "Previous research found that the TOMM40 rs2075650 G allele, independent of the APOE ε4 allele, was associated with depression and obesity, which are risk factors for dementia." (PMID 33790814, 2021). "Other clinically relevant findings include the fact that similar to past studies of CRCD and current models of dementia risk, we found that APOE genotypes do not correspond to a family history of dementia." (PMID 33748669, 2021). "The APOE ε4 allele increased dementia risk by 3 to 6 times but did not modify the associations with diet significantly." (PMID 33748832, 2021). "In this PET study, we investigated the relationship of APOE-ε2 and APOE-ε4 alleles with Aβ and tau load, the two main pathological hallmarks of AD in older individuals without dementia." (PMID 33521872, 2021). "We observed significant interactions between APOE ε4 and AA concentrations, APOE ε4 and ALA concentrations, APOE ε4 and EPA concentrations, and proportions when investing all-cause dementia, and APOE ε4 and EPA concentrations and proportions when investigating AD dementia." (PMID 33573174, 2021).
dementia (continued). "Plasma NfL alone (after adjustment of age, gender and APOE-ε4) was also predictive of dementia." (PMID 34354164, 2021). "ROC curve analysis illustrated all-cause dementia prediction was significantly improved when adding the PRS (c-statistic: 0.792, p < 0.01), APOE (c-statistic: 0.787, p = 0.02) and the PRS & APOE (c-statistic: 0.792, p < 0.01) to age, sex, and education (c-statistic: 0.779)." (PMID 32404947, 2021). "The subjects carrying an APOE ε4 allele without dementia have shown a reduction in the cerebral metabolic rate of glucose." (PMID 34956307, 2021). "Proportion experiencing dementia diagnosis by APOE ε4 status in the ARIC cohort (N = 13,782)a." (PMID 34744974, 2021). "Increased risks of incident all-cause dementia were observed per 25 g/d increments of processed meat in both APOE ε4 carriers and noncarriers." (PMID 33748832, 2021). "In the present study, using two separate cohorts, we modelled disease progression from preclinical AD to AD dementia and determined whether APOE ε4 status and sex affected progression across the entire AD spectrum." (PMID 33603015, 2021). "In one UK study, APOE ε4, ε4 accelerated the risk of severe COVID-19, independent of pre-existing dementia, cardiovascular disease, and type 2 diabetes." (PMID 33668514, 2021). "PRS+APOE (hazard ratio [HR] 1.468, 95% CI 1.335–1.615) and PRS−APOE (HR 1.293, 95% CI 1.157–1.445) were both associated with a significantly increased risk of MCI progression to dementia." (PMID 34465370, 2021). "We also observed that higher concentrations of EPA were associated with a decreased risk for all-cause dementia (HR 0.76 (95% CI 0.61; 0.94)) and AD (HR 0.66 (95% CI 0.51; 0.85)) among apolipoprotein E ε4 (APOE ε4) non-carriers but not among APOE ε4 carriers." (PMID 33573174, 2021). "We used a mixture of generalized gamma distributions to simultaneously estimate time to dementia, time to dementia-free death, and the proportion of individuals with dementia, by APOE ε4 status (≥1 vs. no alleles)." (PMID 34744974, 2021). "AD‐PRSs (including 39 or 57 SNPs) were associated with dementia (57‐SNPs AD‐PRS: hazard ratio 1.09, confidence interval 1.01–1.19, P = .03), particularly in APOE ɛ4 non‐carriers (57‐SNPs AD‐PRS: 1.15, 1.05–1.27, P = 4 × 10–3, 39‐SNPs AD‐PRS: 1.22, 1.10–1.35, P = 2 × 10–4)." (PMID 33532541, 2021). "From competing risk models, compared with APOE ε4 non-carriers, the proportion developing dementia was 26% higher among Blacks (46.3% prevalence, 95% CI: 38.3, 54.4%, among carriers vs. 36.6% prevalence, 95% CI: 33.5, 39.9%, among non-carriers)." (PMID 34744974, 2021). "The effect of age on the severity of COVID-19 disease and APOE in dementia is well known." (PMID 34945790, 2021). "Dementia-only studies could be very important in disentangling potential APOE effects that might be obscured by selection bias affecting SARS-CoV-2 exposure and infection outcome." (PMID 34945790, 2021). "These include mutations in the APOE gene, where the APOE4 variant predisposes to this dementia." (PMID 34944723, 2021). "Our results further suggest that APOE ε4 status may be informative in a CU population even when plasma biomarker values are available, as prediction of subsequent dementia in particular was significantly better when including APOE ε4 as a covariate." (PMID 34117234, 2021). "Firstly, it confirmed that the ε4 allele of APOE is associated with accelerated cognitive decline over the adult life course in both heterozygotes and homozygotes, irrespective of occurrence of dementia." (PMID 34205498, 2021). "Compared with APOE ε4 noncarriers, carriers had increased risks of developing all-cause dementia by ∼3 times, AD by ∼6 times, and VD by ∼5 times, independent of any type of meat consumption." (PMID 33748832, 2021).
dementia (continued). "The apolipoprotein‐E (APOE) ε4 allele is a well‐established genetic risk factor for dementia and AD but it is also a risk factor for disability, indicated by a more rapid motor decline irrespective of cognitive status amongst those with APOE ε4 allele." (PMID 33314384, 2021). "Evidence supporting a connection between APOE and DHA metabolism led to observational studies and clinical trials to test whether long-term DHA supplementation lowers dementia risk or symptoms." (PMID 34276296, 2021). "For instance, racial disparity exists for dementia and the risk gene APOE-ε4 doubles the risk for dementia among whites with no increase among blacks." (PMID 33658917, 2021). "Of N = 13,782 participants, n = 4,281 (31.1%) had ≥1 APOE ε4 allele, n = 2,612 (18.9%) participants had an incident dementia diagnosis, and n = 5,480 (39.8%) died without dementia during the 30 years of follow-up." (PMID 34744974, 2021). "One, we confirmed that the ε4 allele of APOE is associated with accelerated cognitive decline over the adult life course, not only homozygotes but also heterozygotes, irrespective of dementia occurrence." (PMID 33397450, 2021). "Interestingly, in AD mouse models, Apoe expression occurs in the “late response” phase of microglial activation, possibly indicating a role for microglial APOE in chronic neuroinflammation and dementia." (PMID 33841127, 2021). "We found that earlier bedtime, not rise time, was associated with an increased risk of dementia in older Chinese adults without dementia and this was independent of demographics, life style, comorbidities, and APOE genotype." (PMID 33995242, 2021). "The primary aim of the current study was to investigate the associations of VRFs, APOE, and TOMM40 polymorphisms with cognitive performance in Chinese older adults who were free of dementia, with a focus on potential interactions between VRFs and the two genetic polymorphisms." (PMID 33790814, 2021). "Although the difference might be attributed to genetic differences between Japanese and Americans, the Japanese and American cohorts were matched according to APOE genotype, which is the major genetic determinant of dementia." (PMID 34573201, 2021). "With the advantages of definite diagnosis and clinical data from the patients' entire lifespan, we found that even in a small sample, both the APOE ε4 allele and the MAPT H1-haplotype were significantly associated with an accelerated onset of dementia in PD patients." (PMID 33613437, 2021). "While APOE ε4 serves as a strong risk factor for dementia, based on current evidence, it does not appear to be a driving factor in the hearing-dementia association." (PMID 35295208, 2021). "Several studies have examined the effects of APOE ε4 on cognitive decline and dementia in PD." (PMID 33613437, 2021). "Our analysis did not consider the homozygous effects of APOE ε4 on all-cause dementia, but we would expect the heterozygous effect estimates presented here are conservative in comparison." (PMID 34744974, 2021). "Across all included models, never-smoking increased risk for dementia (HR 1.69 [1.06, 2.71], p = 0.03), and having no APOE ɛ4 alleles reduced risk for dementia (HR 0.44 [0.29, 0.67], p < 0.001)." (PMID 32111184, 2020). "The interactions between CRP, the APOE genotype, cardiovascular diseases and cognitive functions and dementia are confusing and might depend on gender, age, and disease such as obesity." (PMID 32646381, 2020). "The joint-effect analyses showed that APOE ɛ4 carriers with passive jobs had an even higher risk of dementia compared to APOE ɛ4 non-carriers with active jobs." (PMID 32081835, 2020). "Moreover, diet can interact with the apolipoprotein E ε4 allele (APOE4), the main genetic risk factor of dementia." (PMID 33255701, 2020).
dementia (continued). "However, the CSF apoE concentrations in other neurodegenerative diseases, e.g., Parkinson’s disease dementia (PDD), progressive supranuclear palsy (PSP), or multiple system atrophy (MSA), are largely unexplored." (PMID 32054532, 2020). "In contrast with total apoE, a higher apoE level in HDL that lacked apoC3 was significantly associated with lower dementia risk." (PMID 32648923, 2020). "Negative APOE ɛ4 status continued to be associated with a lower risk of dementia (HR 0.44 (0.29, 0.67), p < 0.001)." (PMID 32111184, 2020). "Another reason was that lipid levels might be influenced not only by APOE genotype but also by the timing of lipid measurements in relationship to the stage of dementia." (PMID 33312717, 2020). "However, the interaction between psychosocial working conditions and APOE ɛ4 to dementia has rarely been investigated." (PMID 32081835, 2020). "The APOE-ε4 allele is neither necessary, nor sufficient to cause dementia, but the magnitude of increased risk attributed to each copy of the allele is relatively high." (PMID 33143703, 2020). "Being a non-carrier for the APOE ε4 allele was associated with a reduced risk for dementia in every model (p < 0.001)." (PMID 32111184, 2020). "Neurotoxicity and neuroinflammation by APOE ultimately result in neurodegeneration and dementia." (PMID 32466754, 2020). "Potential moderators such as exercise intensity or apolipoprotein-E4 (ApoE4) carriership may determine the magnitude of exercise effects on physical and cognitive functions in patients with dementia (PwD)." (PMID 32192537, 2020). "CAD, stroke, and APOE-ε4 positive were more frequently observed in the new-onset dementia cases." (PMID 33005146, 2020). "In CADASIL, a large cross-sectional study reported from the United Kingdom did not report a significant association between APOE ε4 allele and dementia." (PMID 33328970, 2020). "Again, significant interactions between modified late‐life LIBRA scores and APOE ε4 carrier status were only found in relation to dementia risk (data not shown)." (PMID 31736136, 2020). "Lifelong non-smoking status was associated with a higher risk of incident dementia in all three models; negative APOE ɛ4 carrier status was again associated with a lower risk of incident dementia in the three models." (PMID 32111184, 2020). "Tat and ApoE may have similar or overlapping signaling pathways, and thus Tat needs to be considered as important in the pathogenesis of dementia in HAND." (PMID 32158701, 2020). "Instead, tau pathology density in the frontal cortex was significantly associated with dementia and had a much greater effect in APOE e4 positive than negative participants." (PMID 32076055, 2020). "We aimed to 1) examine the association between job demand-control status and dementia, 2) verify the working conditions-APOE ɛ4 interaction, and 3) investigate whether longer work duration amplifies the impact of detrimental working conditions on dementia." (PMID 32081835, 2020). "This study showed that CMBs and dementia may be attributed to the interaction between the CCM2 variant and the APOE genotype." (PMID 33352859, 2020). "We tested if age, sex, education level, APOE status, family history for dementia, memory complaints or memory scores, previously collected in these cohorts, could predict participation and amyloid status." (PMID 31907067, 2020). "These neuroimaging results suggest that APOE ε4 carriers develop functional brain abnormalities several decades before the possible onset of dementia, and the results are in line with our finding that a high percentage of those with clinical AD were APOE ε4 carriers." (PMID 32632135, 2020). "In addition, genetic factors for the development of dementia have also been examined, with the apolipoprotein E (APOE) genotype being identified as the most potent genetic risk factor for the development of AD." (PMID 33129280, 2020).
dementia (continued). "This complexity measure has been used in several studies on dementia due to AD, but none has yet analyzed its role to reflect alterations in neural patterns associated to the ApoE genotype." (PMID 32664228, 2020). "Indeed, social network size was found to be positively associated with maintenance of cognitive performance within the normal range over a longer period of time, thus postponing dementia onset independently of APOE status." (PMID 33192732, 2020). "In this study, we observed that the risk of dementia in the patients with APOE ε4 allele was higher than those without APOE ε4 allele irrespective of treatment they received." (PMID 32581766, 2020). "Moreover, higher levels of APOE in APOC3-free HDL particles in the plasma have been associated with better cognitive performance and reduced risk of dementia in humans." (PMID 33148290, 2020). "There is no direct association of APOE with other atypical parkinsonism syndromes with dementia such as corticobasal degeneration (CBD), multiple system atrophy (MSA) and progressive supranuclear palsy (PSP)." (PMID 32005122, 2020). "Therefore, future studies would benefit from evaluating the APOE genotype in dementia patients with CMV tissue-invasive diseases." (PMID 32466754, 2020). "The results indicate that neither the concentrations of total apoE nor the different apoE isoforms in CSF are associated with APOE-ε4 carrier status, Aβ status, or clinical dementia diagnoses." (PMID 32054532, 2020). "A study on binge Finnish drinkers without the APOE-4 allele reported an insignificantly reduced risk of dementia, whereas infrequent binge drinkers with the APOE-4 allele displayed significant increase in the risk of dementia." (PMID 31941117, 2020). "In conclusion, the ApoE e4e4 allele increases risks of severe COVID-19 infection, independent of preexisting dementia, cardiovascular disease, and type-2 diabetes." (PMID 32451547, 2020). "The cognitive impairment progression and the risk of dementia were higher in the hypertensive patients with APOE ε4 allele than in those without APOE ε4 allele." (PMID 32581766, 2020). "In the same model, carrying no APOE ɛ4 alleles was associated with a lower risk for incident dementia (HR 0.45 (0.30, 0.69), p < 0.001)." (PMID 32111184, 2020). "APOE ɛ4 negative carrier status associated with a lower risk for incident dementia in each of the three models." (PMID 32111184, 2020). "However frontal cortex tau pathology displayed a greater effect on dementia in APOE ε4 positive participants (OR = 12.188, p = 0.038) than in APOE ε4 negative participants (OR = 2.542, p = 0.001)." (PMID 32076055, 2020). "APOE exists in three isoforms, although APOE4 prevails as the strongest predictor of dementia." (PMID 33153085, 2020). "In a prospective cohort of older adults with rigorous follow-up of dementia, the apoE level in HDL that lacked apoC3 was associated with better cognitive function and lower dementia risk." (PMID 32648923, 2020). "In the joint effect analyses among the younger-old, APOE ɛ4 carriers with passive jobs had a higher risk of dementia, as compared to APOE ɛ4 non-carriers with active jobs (HR 8.21, 95% CI 2.91-23.15)." (PMID 32081835, 2020). "APOE ε4, diabetes, heart disease, stroke, and delirium increase dementia incidence at p < 0.05." (PMID 32767997, 2020). "However, as far as data are available, factors such as apolipoprotein E genotype or a family history of dementia should be included in future similar studies." (PMID 32582724, 2020). "The cytokines IL-13 and IL-1α were significantly associated with less tau pathology in APOE ε4 negative participants and were not independently predictive of dementia." (PMID 32076055, 2020). "The UKBB study concluded that ApoE e4 allele increases the risk of severe COVID-19 infection, independent of pre-existing dementia, cardiovascular disease, and type-2 diabetes." (PMID 33414783, 2020).